BRAF (B-Raf proto-oncogene, serine/threonine kinase)
Diseases named in the same sentence as BRAF in open-access papers (continued):
Sharing a sentence is not in itself a finding about the gene and the disease.
tumor (continued). "While AZD6244 (selumetinib) is a high-potency MEK inhibitor, resistance to therapy and tumor progression occurs in some patients with BRAF mutations." (PMID 32916316, 2020). "The BRAF V600E mutation in tumor tissues was detected by amplification-restriction mutation system polymerase chain reaction (ARMS-PCR), and the serum levels of Tg, TSH, Tg-Ab, and Tpo-Ab were measured by chemiluminescence after iodine-131 treatment." (PMID 31949496, 2020). "For example, miRNAs correlate with microsatellite instability (MSI) status, tumor location, BRAF and KRAS mutation and tumor stage." (PMID 30786859, 2019). "One study analyzed 40 NET of the gastroenteropancreatic system and found one mutation in BRAF (V600E) in a single tumor in the cohort and reported activated levels of phospho-ERK in nearly all tumors in the cohort." (PMID 31158244, 2019). "Metastatic CMM tumors displayed moderate to high cytoplasmic and membranous ERBB3 and MET expression in 12/13 (92%) and 9/21 (43%) BRAF-mutated tumor samples, respectively." (PMID 31506424, 2019). "We detected BRAF p.V600E mutations in ctDNA of three patients, in two patients by sequencing and in one by dPCR, and these BRAF mutations were also present in tumor tissue." (PMID 31350822, 2019). "The MSI status is closely associated with other characteristics of the tumor, such as BRAF mutations, early stage, proximal location, and higher degree of immune infiltration." (PMID 31296182, 2019). "To see if the patients' cfDNA levels are influenced by the tumor BRAF mutation status, we compared the cfDNA levels of patients whose tumors harbored the BRAFV600E mutation and those with wild type tumors." (PMID 31998653, 2019). "We explored the concordance between the mutational status of the RAS and BRAF in tumor tissue and plasma." (PMID 31319569, 2019). "A major value-added of our study is the assessment of the relationship between RAS, PIK3CA, and BRAF tumor mutation status with clinical response to chemotherapy in the metastatic setting." (PMID 31036005, 2019). "For prognostic assessment, tumor BRAF mutational status should be assessed alongside the assessment of tumor RAS mutational status." (PMID 30811471, 2019). "Tumours with the BRAF mutation were more likely to present with peritoneal metastases and aggressive biology." (PMID 31065262, 2019). "All 30 cases with BRAF V600E mutation exhibited uniform, unequivocal, diffuse, cytoplasmic staining in majority of tumor cells with stain intensities of 1–2.75 and background ≤0.25." (PMID 29127628, 2019). "In BRAF-mutated tumours, the median PFS and OS were 8.3 versus 7.6 months and 22 versus 11.7 months, respectively." (PMID 30585257, 2019). "To do so, we compared the two A2B5+, BRAF fusion-associated clusters to the tumor-associated cells in the other three clusters." (PMID 31427603, 2019). "The BRAF V600E mutation was present in two out of 30 patients analyzed (7%; one supratentorial/hemispheric and one infratentorial/midline tumor)." (PMID 31362435, 2019). "We also compared the frequencies of PTC patients' disease status to their tumor BRAF hotspot mutation status." (PMID 31998653, 2019). "A broad approach with a panel of genes should be relevant to detect actionable mutations in other genes than KRAS, NRAS and BRAF and discuss cases in multidisciplinary molecular tumour boards." (PMID 31265477, 2019). "This retrospective case series characterizes the largest series to date of BRAF V600E mutated pediatric JXG family neoplasms, all of which were first diagnosed with CNS disease and share a striking young male predominance with aggressive disease." (PMID 31685033, 2019). "The lower frequency of BRAF mutations in MSI-H1 accompanied by a relatively worse prognosis inspired us to identify the potential tumor microenvironment component underlying this contradictory association." (PMID 31331345, 2019).
tumor (continued). "Cell-free circulating tumor (ct) DNA was measured as either the fraction with Neuropeptide Y (NPY) methylated DNA or KRAS/NRAS/BRAF mutated ctDNA." (PMID 31731482, 2019). "In conclusion, this interpretation algorithm can be derived from the data of transmural biopsies in our study: In cases of TCC with BRAF mutation in terriers, a high-grade tumor with increased COX-2 expression is most likely." (PMID 30893857, 2019). "Herein, we map the clonal trajectory of BRAF mutation-bearing cells across diverse variants and cancer types and exploit the variation in the architectures of BRAF-driven tumors to optimize tumor sensitivity." (PMID 31723142, 2019). "The tumor with a maximum diameter (Dmax) larger than 5 mm was shown to be significantly correlated with the BRAF mutation in a multivariate analysis (OR 5.52, 95% CI 1.51-26.42, P = 0.033)." (PMID 30915113, 2019). "This underlines the need to not only discriminate the MSI status of a tumor in any classification, but to also include information on the BRAF and KRAS mutational status." (PMID 31296182, 2019). "Genetic analysis of the tumor was performed using a diagnostic biochip for the detection of somatic mutations in the BRAF, NRAS, KIT, GNAQ, GNA11, MAP2K1, and MAP2K2 genes, Sanger sequencing for searching germinal mutations in the CDKN2A gene." (PMID 30782194, 2019). "We observed differences in RET tumor staining between adult and pediatric patients, and differences in BRAF V600E mutation between ATA risk groups." (PMID 30552739, 2019). "Experimental studies, both on cancer cell lines and in animal models, provide strong evidence for a correlation between BRAF mutation and altered chemokine secretion in the tumor microenvironment." (PMID 31762942, 2019). "BRAF V600E CNS-JXG neoplasms appear associated with male gender and aggressive disease presentation including pediatric ECD." (PMID 31685033, 2019). "Mutations of BRAF genes (B-isoform of rapidly accelerated fibrosarcoma) are a common cause of tumor formation in humans and lead to abnormal proliferation and differentiation of cells." (PMID 30893857, 2019). "The association between the factor, including gender, age, or tumor size, and the BRAF mutation in PTMC has been unclear." (PMID 30915113, 2019). "On the other hand, BRAF non-V600E mutations occur at approximately 1 to 5%, and show different clinicopathological characteristics, such as left-sided tumor and better prognosis, than BRAF V600E mutation." (PMID 30792536, 2019). "Aim of the present review is to describe currently available data regarding the role of BRAF mutations as well as the effects of BRAF-inhibitors in the tumor micro-environment." (PMID 31762942, 2019). "The mutations identified in APC, GNAS, and BRAF were found in serous (1/64, 1.6%), endometrioid (1/5, 20.0%), and mucinous (1/1, 100.0%) tumor samples, respectively." (PMID 31197119, 2019). "Although the BRAF V600E mutation constitutes the majority of molecular alterations in ECD and LCH, only three reported JXG neoplasms, all in male pediatric patients with localized central nervous system (CNS) involvement, are known to harbor the BRAF mutation." (PMID 31685033, 2019). "In these PDX models, prolonged treatment with larotrectinib resulted in the outgrowth of tumours with a newly acquired BRAF-V600E mutation, thus replicating the development of this bypass mutation in the clinical setting and in this case report." (PMID 31605106, 2019). "Despite the uncertainties regarding the classification of eGBMs and its molecular relationship to other tumor entities, an existing BRAF V600E mutation can potentially be exposed to an established targeted treatment." (PMID 31181803, 2019). "In stage II patient 249‐CB‐P, the BRAF mutation in the tumor was detected in the corresponding plasma sample with an allele frequency of 0.05 (27 mutation events)." (PMID 31134762, 2019).
tumor (continued). "Sensitivity to RAF and MEK inhibitors varies among BRAF mutations and between tumor types as only class I BRAF V600 mutations are sensitive to clinically available RAF inhibitors." (PMID 31466300, 2019). "Nevertheless, for three out of four patients with the mutation in tumor tissue, the BRAF mutation was also detected in ctDNA." (PMID 31350822, 2019). "In this analysis, we reported that 14 of 111 patients (13%) had SRC mutation, which was significantly associated with left-sided tumor and liver metastasis compared to BRAF V600E mutation." (PMID 30792536, 2019). "The presence of circulating free tumour DNA for the mutations BRAF, K-ras, N-ras, and PIK3CA mutations has been used to identify patients with MRD and also as a marker for the resistance to EGFR therapy, such as cetuximab or panitumumab." (PMID 31281432, 2019). "Previous studies focusing on BRAF mutations found a concordance between plasma ctDNA and tumor BRAF mutations of 75–76%." (PMID 31671846, 2019). "The BRAF score were inversely proportional to the time to 1 cm3 (inset), indicating an association between tumor doubling times and BRAF activity." (PMID 31723142, 2019). "Droplet Digital PCR (ddPCR) was performed to detect common point mutations in the KRAS and BRAF oncogenes in cfDNA from 65 patients and compared to mutations in tumor tissue." (PMID 31134762, 2019). "In conclusion, PTEN alterations seem to be more frequently correlated with right-sided tumors, microsatellite instability, BRAF mutations, lymph node metastases, and a higher tumor stage." (PMID 31717544, 2019). "Our results suggest that high tumor PD-L1 expression and BRAF V600E mutation are associated with poor outcomes in patients with NPC." (PMID 31664962, 2019). "The frequencies of RAS and BRAF mutations in mCRC tumor tissues or ctDNA are reported to be around 50% and 5–10%, respectively." (PMID 31164904, 2019). "To further confirm the utility of liquid biopsies for biomarker detection, we analyzed the concordance between BRAF mutation status in the original tumor and in liquid biopsy." (PMID 31881643, 2019). "Overall, 14 out of 25 studies scored cases positive for BRAF V600E mutation when uniform or nearly uniform, diffuse staining was present in tumor cells or when the majority (≥ 75%) of tumor cells exhibited unequivocal cytoplasmic staining." (PMID 29127628, 2019). "The copper (Cu) dependence of MEK1/2 dysfunctional signalling is an important target to inhibit tumour cells with BRAF or KRAS mutations." (PMID 30792807, 2019). "Compared with sham treated controls, BRAF-mutated tumor xenografts were smaller, less invasive and showed a lower proliferation index when mice received BRAF inhibitors." (PMID 31762942, 2019). "We posited that the fitness of a particular BRAF-variant will determine the host tumor’s clonal architecture." (PMID 31723142, 2019). "For 133 (32.6%) patients, microsatellite instability (MSI) status was available; including 29 of the 30 patients with tumor tissue BRAF mutation and 26 of the 27 patients with BRAF plasma mutation." (PMID 31319569, 2019). "Searching for the primary gene “BRAF” from the “GENES” tab in SL-BioDP shows the alteration profiles of BRAF in 18 different tumor types, both in terms of mutations and gene expression." (PMID 31671773, 2019). "Multivariable-adjusted hazard ratios are adjusted for age, sex, tumour location, BRAF mutation, MMR-D/POLE mutation, CIN and adjuvant bevacizumab." (PMID 31388185, 2019). "BRAF V600E was the only mutation in which more than 1 aggressive feature within one tumour was present." (PMID 31623671, 2019). "BRAF V600E tumours were 5.91 times (relative risk) more likely to demonstrate aggressive features when compared to tumours where no mutation was detected (95% CI 2.49-14.0, p-value 0.0001)." (PMID 31623671, 2019). "Of the 407 patients, 7.4% (30/406) and 6.6% (27/406) had BRAF mutations in tumor tissue and plasma, respectively." (PMID 31319569, 2019).
tumor (continued). "Together with the identification of a kinase-impairing BRAF mutation in a primary resistant tumor (C1011BL), this substantiates a role of BRAF D594 mutations in CET resistance." (PMID 31287991, 2019). "Aside from KRAS/BRAF mutations, TKIs-treated tumors can gradually generate persistent genetic alterations and allow tumor toleration through compensatory pathways." (PMID 31703359, 2019). "Dense eosinophilic cytoplasm has been shown in previous studies of SBT to be a distinctive feature of tumor cells harbouring the BRAF-mutation." (PMID 31839880, 2019). "BRAF and NRAS mutations were mutually exclusive except for the single tumor harboring the BRAF V600R mutation, which was also NRAS c61 mutant." (PMID 30672666, 2019). "The second round of tumor tissue analysis by next-generation sequencing (NGS) was possible in only two out of four patients with the BRAF mutation in plasma." (PMID 31319569, 2019). "The prevalence of BRAF V600E mutation in plasma was 11.4% versus 12.9% in tumor tissue, resulting in the concordance of 95.7% (kappa coefficient of 0.80)." (PMID 31319569, 2019). "The VAF of BRAF mutations were relatively concordant with that of RAS mutations, except for one tumor with coexistence of class-2 BRAF mutation and NRAS mutation." (PMID 31277584, 2019). "Cox proportional hazard regression models were used to estimate adjusted hazard ratios (HR) and 95% confidence intervals (CI) of survival after CRC, including adjustment for tumor stage, microsatellite instability, and BRAF mutation status." (PMID 31340858, 2019). "Here, we report BRAF mutation status analysis in paired tumor tissue and plasma samples of mCRC patients included in the AGEO RASANC prospective cohort study." (PMID 31319569, 2019). "A second tumor (patient #1) was found to have three disease associated variants: BRAF c.1799 T > A p.(V600E), NF1 c.7079_7082delTTAT p.(F2360Wfs*35), and TSC1 c.2074C > T p.(R692*)." (PMID 31046843, 2019). "BRAF and KRAS are mutually exclusive, and 1 tumour harboured a double mutation in the BRAF and NRAS genes." (PMID 30837681, 2019). "Despite substantial advances in the development of therapeutics focused on MAPK pathway inhibition in BRAF-mutated cancers, resistance and subsequent tumor relapse remain a major challenge to the durable success of these therapies." (PMID 31581557, 2019). "These tumors are typically treated with surgery; however, residual tumor and recurrence can pose a treatment quandary because little is known about the genetic landscape of these tumors beyond two defining mutations: BRAF V600E and CTNNB1." (PMID 31712784, 2019). "Twenty-eight tumors (13%) harbored a BRAF mutation including one tumor with two BRAF mutation p.S467L and p.V600M." (PMID 31036005, 2019). "In spite of these cross-sectional studies using imaging, there is a lack of comprehensive understanding of the association between tumor glucose metabolism, differentiation and BRAF mutation." (PMID 31888560, 2019). "We report two interesting cases of SMECE with concurrent papillary thyroid carcinoma (PTC), both harboring the B-Raf proto-oncogene, serine/threonine kinase (BRAF) V600E activating mutation in the SMECE tumor." (PMID 31882020, 2019). "Since BRAF V600E mutation is a driver mutation, a majority of tumor cells should express this mutated protein." (PMID 29127628, 2019). "Conversely, Cohen and colleagues showed that CIMP+ status based on the same panel of methylation markers did not affect overall survival in CRC patients, but it was associated with right-side tumor location and BRAF mutations." (PMID 31390840, 2019). "CIMP-positive tumours are generally thought to develop through the serrated neoplasia pathway and are associated with BRAF mutation." (PMID 31690257, 2019). "The biopsy was morphologically consistent with metastatic SMECE, and the tumor was also positive for BRAF V600E mutation." (PMID 31882020, 2019).
tumor (continued). "BRAF mutation both in the tumor tissue and plasma was strongly associated with the presence of the MSI status." (PMID 31319569, 2019). "The BRAF gene was mutated in 8 tumor samples (8.8%), showing 8 missense somatic mutations mutually exclusive with KRAS, all previously reported as somatic mutations in CRC." (PMID 31548566, 2019). "Patients with any RAS/BRAF mutations in either tumor tissue or ctDNA had less treatment benefit than patients who had a negative test result." (PMID 31350822, 2019). "Here, the authors highlight how distinct BRAF mutations affect the clonal dynamics and architecture of emergent tumours, with potential implications for therapeutic intervention." (PMID 31723142, 2019). "Radiographic features of CNS-JXG varied but typically included enhancing CNS mass lesion(s) with associated white matter changes in a subset of BRAF V600E neoplasms." (PMID 31685033, 2019). "The most common approach for the detection of BRAF mutation is sequencing of tumor DNA, for example Sanger sequencing, pyrosequencing and high resolution melting." (PMID 29127628, 2019). "BRAF mutations were identified in six samples (7.5%): two tumors harbored V600E mutations, one tumor each expressed K601E, T599K, and T310I mutations, and one tumor expressed both G596D and E451K BRAF." (PMID 31158244, 2019). "This retrospective case series seeks to redefine the clinicopathologic spectrum of pediatric CNS-JXG family neoplasms in the post-BRAF era, with a revised diagnostic algorithm to include pediatric ECD." (PMID 31685033, 2019). "An increasing number of studies that include meta-analyses have been able to demonstrate an association between BRAF V600E status and aggressive tumour behavior." (PMID 31623671, 2019). "This encouraging development in the treatment of BRAF mutated tumor entities gives hope for the further advancement of personalized tumor treatment." (PMID 31181803, 2019). "We examined the effects of introducing BRAFi or MEKi in tumor cells with varying strengths of BRAF-variant selection." (PMID 31723142, 2019). "In total, 70 patients had paired tumor and plasma available for BRAF V600E mutation status analysis." (PMID 31319569, 2019). "BRAF is commonly mutated in some cancers, including 4.26% of the TCGA tumor samples with LUAD histology." (PMID 31671773, 2019). "BRAF-mutated cells overcome OIS by utilizing epigenetic reprogramming to their advantage in promoting tumor formation." (PMID 31581557, 2019). "WGS was performed on the recurrent tumor, revealing mutations associated with intracranial pilocytic astrocytoma, including BRAF V600E and canonical hTERT promoter mutation." (PMID 31822682, 2019). "In previous work, we have described the presence of tumor cells with abundant dense eosinophilic cytoplasm to be a characteristic morphologic feature in BRAF-mutated SBTs, a finding that has subsequently been confirmed independently by another group." (PMID 31839880, 2019). "Tumor cells showing BRAF V600E mutation tend to have increased cytokine secretion such as that of interleukin (IL)-1β, IL-6, and IL-8, because cytokines such as tumor necrosis factor alpha or IL-1β increase ATX and LPA levels." (PMID 31455351, 2019). "In the patients with liver metastases tested for BRAF mutations in both the tumor tissue and plasma (n = 405), the kappa coefficient was 0.91 (95% CI: 0.81–1.00) and the accuracy was 98.6% (95% CI: 96.5–99.6%)." (PMID 31319569, 2019). "From relapsed tumor procured at autopsy, we established a cell line retaining the BRAF V600E mutation, TERT promoter mutation and CDKN2A/2B loss." (PMID 31345255, 2019). "A low percentage of the mutant BRAF alleles was also detected in DNA extracted from CPTC with lymphocytic infiltration in tumor stroma." (PMID 31810221, 2019). "V600E c.1799T>A alterations accounted for 99% of BRAF mutations, with only one exception, a single tumor with a 1799_1801delTGA, V600E/K alteration." (PMID 30995742, 2019).